PSMG4 (proteasome assembly chaperone 4)
Description:
Chaperone protein which promotes assembly of the 20S proteasome.
Synonyms: Pba4; C6orf86; PAC4; bA506K6.2
Tractability: PROTAC: ubiquitination databases record sites on it; its protein half-life has been measured.
Gene: Protein-coding gene on chromosome 6 (3,231,403 to 3,304,020, forward strand). Ensembl gene ENSG00000180822.
Subcellular location (Human Protein Atlas): Mitochondria; Nucleoplasm
Pathways (Reactome):
Metabolism of proteins: Proteasome assembly
Gene Ontology:
Molecular function: protein-containing complex binding
Biological process: proteasome core complex assembly; proteasome assembly
Cellular component: protein folding chaperone complex; cytosol; protein-containing complex
Genetic constraint (gnomAD): Loss-of-function variants: 10 observed, 9.33 expected, observed/expected ratio (o/e) 1.07, 90% interval 0.66 to 1.74. That is too few expected variants to judge how well the gene tolerates losing a copy. Missense variants: 198 observed, 135.28 expected, observed/expected ratio (o/e) 1.46, 90% interval 1.3 to 1.65. Synonymous variants: 95 observed, 60.23 expected, observed/expected ratio (o/e) 1.58, 90% interval 1.33 to 1.86.
Homologues: Orthologues: chimpanzee PSMG4 (100% identical), guinea pig PSMG4 (92% identical), mouse Psmg4 (89% identical), macaque PSMG4 (71% identical), dog PSMG4 (67% identical), rat Psmg4 (56% identical).
Diseases named in the same sentence as PSMG4 in open-access papers:
PSMG4 is named in the same sentence as 6 diseases in open-access papers, as found by Europe PMC text mining. Sharing a sentence is not in itself a finding about the gene and the disease. The quoted sentences say what the papers report.
lung carcinoma (2 papers, 2023 to 2024). "High expression levels of PSMG4 were identified as a potential biomarker for adverse OS in lung cancer, while PSMG1 showed prognostic significance at the pan-cancer level." (PMID 39335660, 2024). "Moreover, numerous experiments on the NSCLC-derived A459 cell line revealed that p-Akt inhibition helped increase apoptosis and reduce radio-resistance 75-77, and bioinformatics data also presented DNA methylation expression levels of PSMG4 in lung cancer." (PMID 36619227, 2023). "Similarly, such immune infiltration patterns of PSMG4 were recorded in LUAD patients via a TIMER analysis, which neatly supports the strong biological associations between PSMG4 and HSP90AA1 in the context of lung cancer." (PMID 36619227, 2023). "Additionally, similar immune infiltration patterns between PSMG4 and HSP90AA1 also suggested that PSMG4 may play a certain role in the immune-suppressive TME which is common among lung cancer patients." (PMID 36619227, 2023).
breast carcinoma (1 paper, 2026). "The proteasome assembly chaperone (PSMG) gene family (comprised of PSMG1, PSMG2, PSMG3, and PSMG4) plays a critical role in proteasome biogenesis; however, its involvement in breast cancer remains poorly understood." (PMID 41869439, 2026).
cancer (2 papers, 2023 to 2024). A tumor composed of atypical neoplastic, often pleomorphic cells that invade other tissues. "Further in-depth experiments are mandated to extensively explore PSMG4's key roles in the underlying pathogenesis and immune crosstalk in LUAD progression and metastatic spread that participate in cancer development." (PMID 36619227, 2023). "It was suggested that PSMG family member overexpression may promote tumor growth, and overexpression of PSMG1, PSMG3, and PSMG4 may further promote the development of cancer metastasis." (PMID 36619227, 2023).
tumor (1 paper, 2023). "Surprisingly, we found that PSMG4 had positive correlations with the tumor stage, especially with the highest expression in stage 4 LUAD." (PMID 36619227, 2023).
PSMG4 also shares sentences with these, for which no sentence is quoted: hay fever (1 paper); Huntington disease (1).